RNU6-656P (RNA, U6 small nuclear 656, pseudogene)
Gene: Small nuclear RNA gene on chromosome 8 (46,831,050 to 46,831,156, forward strand). Ensembl gene ENSG00000252594.
Homologues: Orthologues: chimpanzee U6 (93% identical), pig U6 (92% identical), rat LOC120095502 (91% identical), macaque U6 (85% identical). Paralogues in human: RNU6-17P (92% identical), RNU6-18P (92% identical), RNU6-854P (92% identical), RNU6-1 (91% identical), RNU6-12P (91% identical), RNU6-13P (91% identical), RNU6-15P (91% identical), RNU6-19P (91% identical), RNU6-2 (91% identical), RNU6-31P (91% identical), RNU6-32P (91% identical), RNU6-3P (91% identical), and 1288 more.